SMYD3 (SET and MYND domain containing 3)
Diseases named in the same sentence as SMYD3 in open-access papers (continued):
Sharing a sentence is not in itself a finding about the gene and the disease.
non-small cell lung carcinoma (3 papers, 2021 to 2025). A group of at least three distinct histological types of lung cancer, including non-small cell squamous cell carcinoma, adenocarcinoma, and large cell carcinoma. "In non-small cell lung cancer, SMYD3 binds to the anoctamin-1 (ANO1) promoter region, which is enriched with H3K4me3, thereby increasing ANO1 transcription and regulating cancer cell proliferation." (PMID 39482529, 2024). "Additionally, SMYD3 overexpression promotes non-small cell lung cancer cell proliferation, whereas SMYD3 knockdown inhibits cell proliferation." (PMID 39482529, 2024). "Moreover, high SMYD3 expression renders non-small cell lung cancer cells chemoresistant to cisplatin, and the mechanism is mediated by its coregulator ANKHD189." (PMID 39482529, 2024). "Our data demonstrated that OE-Smyd3 activates MEK/ERK signaling, and it was reported that the protein level of SMYD3 is sensitive to the combination treatment of trametinib (Tra, which inhibits MEK1 and MEK2) and navitoclax in PDX (patient-derived xenografts) for non-small cell lung cancer." (PMID 40157910, 2025).
Obesity (3 papers, 2022 to 2024). Accumulation of substantial excess body fat. "Strikingly, GWAS studies have previously highlighted SNPs associated to phenotypes linked to inflammation and/or obesity, such as BMI and waist to hip ratio in humans for SMYD3, ELP6 and KDM1A." (PMID 38148333, 2024). "Consistent with this idea, a differential DNA methylation pattern at the SMYD3 gene was recently found in insulin sensitive women with obesity." (PMID 38148333, 2024). "Future studies will be necessary to fully unravel SMYD3 function in adipose tissue and to understand how its activity can be modulated in physiology and disease, more precisely in the context of healthier obesity." (PMID 38148333, 2024).
oral squamous cell carcinoma (3 papers, 2016 to 2024). "According to machine learning data from 429 chromatin regulators, SMYD3 is aberrantly expressed in oral squamous cell carcinoma, and SMYD3 expression is associated with oral squamous cell carcinoma formation and poor prognosis." (PMID 39482529, 2024).
Autoimmunity (2 papers, 2017 to 2019). The occurrence of an immune reaction against the organism's own cells or tissues. "SMYD3 promotes formation of inducible regulatory T cells and is involved in reducing autoimmunity." (PMID 28050603, 2017). "In addition, SMYD3 was found to promote formation of inducible regulatory T cells and may be involved in reducing autoimmunity." (PMID 28050603, 2017). "Like in panel, I autoimmunity appears to be in play with proteins AFF3, SMYD3, and LRP1." (PMID 31026304, 2019).
breast tumor (2 papers, 2024 to 2025). "Moreover, the broad potential of SMYD3 inhibition is strengthened by our previous analysis of publicly available human cancer data from The Cancer Genome Atlas (TCGA) dataset indicating that SMYD3 mRNA levels have been found increased in around 30% of colorectal, pancreatic, and breast tumors." (PMID 38812026, 2024).
cervical carcinoma (2 papers, 2010 to 2017). A carcinoma arising from either the exocervical squamous epithelium or the endocervical glandular epithelium. "It is known that knockdown of SMYD3 inhibits cervical carcinoma cell growth and invasion and that mutations in the 5'-flanking region of SMYD3 may represent a risk factor for human cancer." (PMID 20525348, 2010). "It is also known that SMYD3 plays crucial roles in HeLa cell proliferation and migration/invasion, so it has been suggested that it may be a useful therapeutic target in human cervical carcinomas." (PMID 20525348, 2010).
clear cell renal cell carcinoma (2 papers, 2022 to 2025). "Cancer cell‐intrinsic SMYD3 orchestrates an immunosuppressive microenvironment and impairs the response to PD‐1 blockade by reprogramming immune cells landscape in the tumor microenvironment of clear cell renal cell carcinoma (ccRCC)." (PMID 40548645, 2025). "LncRNA CDKN2B-AS1 was stabilized by IGF2BP3, recruited CBP and SMYD3 and activated NUF2 transcription in renal clear cell carcinoma." (PMID 35676262, 2022).
cyst (2 papers, 2024). A sac-like closed membranous structure that may be empty or contain fluid or amorphous material. "The knockout of SMYD3 in PKD1 mutant mouse kidneys induced cyst-lining epithelial cell apoptosis as analyzed by TUNEL (terminal deoxynucleotidyl transferase dUTP nick end-labeling) staining." (PMID 38540216, 2024). "We have provided evidence that the double conditional knockout of PKD1 and SMYD3 delays cyst growth, improves renal function, and normalizes PKD-associated signaling pathways and cell cycle effectors." (PMID 38540216, 2024). "We further found that SMYD3 was increased in the cyst-lining epithelial cells in kidneys from the ADPKD patients when examined with immunohistochemistry analysis." (PMID 38540216, 2024). "Genetic knockout of SMYD3 in a PKD1 knockout mouse model delayed cyst growth and improved kidney function compared with PKD1 single knockout mouse kidneys." (PMID 38540216, 2024). "In summary, our study demonstrates that SMYD3 is an epigenetic factor that is important for cyst growth in ADPKD." (PMID 38540216, 2024). "In summary, our results demonstrate that overexpression of SMYD3 contributes to cyst progression and suggests targeting SMYD3 as a potential therapeutic strategy for ADPKD." (PMID 38540216, 2024). "The knockout of SMYD3 delayed cyst growth and improved kidney function in postnatal day 7 (P7) DKO kidneys compared to age-matched PKD1 single knockout (PKD1 SKO) kidneys, as shown by the decrease in the kidney-weight-to-body-weight (KW/BW) ratio, cystic index, and blood urea nitrogen (BUN) levels." (PMID 38540216, 2024). "Interestingly, we found that the treatment of mIMCD3 cells with TNF-α, which has been demonstrated to enhance cyst growth, increased the expression of SMYD3, suggesting a positive feedback loop of SMYD3/TNF-α/NF-κB/SMYD3, in a similar manner to SMYD2." (PMID 38540216, 2024).
esophageal cancer (2 papers, 2018 to 2020). A primary or metastatic malignant neoplasm involving the esophagus. "A homozygous [[CCGCC]3] variable nucleotide tandem repeat (VNTR) in the SMYD3 promoter is associated with increased risk of CRC, hepatocellular (HCC), BrCA and esophageal cancer (EC) cancer in relation to tobacco smoking." (PMID 31935919, 2020). "SMYD3 also regulates transcription of EZR and LOXL2 genes by direct recruitment to their promoter regions, thus sustaining proliferative, migration and invasion signaling in esophageal cancer cells." (PMID 31935919, 2020).
fibrosarcoma (2 papers, 2016 to 2020). A malignant mesenchymal fibroblastic neoplasm affecting the soft tissue and bone. "We previously reported that SMYD3 regulates Mmp-9 transcription in fibrosarcoma cells." (PMID 33244033, 2020).
glioma (2 papers, 2020 to 2021). A benign or malignant brain and spinal cord tumor that arises from glial cells (astrocytes, oligodendrocytes, ependymal cells). "Kaplan–Meier analysis showed significantly longer survival in patients with gliomas with low SMYD3 expression as compared to patients with high SMYD3 expression." (PMID 33637115, 2021). "SMYD3 depletion resulted in decreased cell proliferation and colony formation in human glioma cell lines." (PMID 33637115, 2021). "Additionally, SMYD3 expression was higher in high pathologic grade gliomas when compared to low pathologic grade." (PMID 33637115, 2021). "SMYD3 activity was also correlated to the expression of RIZ1, a tumor suppressor protein silenced in a variety of cancers such as liver, breast, colon, gastric and glioma and whose expression is linked to G2/M arrest and induction of apoptosis in cancer cells." (PMID 31935919, 2020). "First, IHC showed that SMYD3 is overexpressed human glioma samples but not in normal brain tissues." (PMID 33637115, 2021).
hyperlipidemia (2 papers, 2020 to 2022). "Some researchers have established cellular and animal models to study the effects of chitosan on hyperlipidemia and have shown that chitosan considerably reduced lipid accumulation in HepG2 cells and the expression of HMGCR, SET and MYND domain containing 3 (SMYD3) in animal models." (PMID 32726987, 2020).
Hypertension (2 papers, 2017 to 2020). The presence of chronic increased pressure in the systemic arterial system. "Further studies will investigate the function of intrarenal Smyd3 in the regulation of intrarenal AGT expression and the development of hypertension and RAS associated kidney injury." (PMID 28572913, 2017). "All these additional results above extended our findings for the role of Smyd3 and p21 in vascular aging and related diseases, combined to indicate the regulatory role of Smyd3‐p21 axis in hypertension and atherosclerosis, implying their biomedical importance in therapy of vascular diseases." (PMID 32779886, 2020).
medulloblastoma (2 papers, 2022 to 2024). A malignant, invasive embryonal neoplasm arising from the cerebellum. "SPRIGHTLY-driven SMYD3 regulation increases the expression of EGFR signaling genes in G4 medulloblastoma cells." (PMID 39482529, 2024).
melanoma (2 papers, 2021 to 2024). A malignant, usually aggressive tumor composed of atypical, neoplastic melanocytes. "As with HULC, the possible role of SMYD3 in melanoma appears to be unreported." (PMID 33769711, 2021).
ovarian tumor (2 papers, 2021). "According to the previous work of our team, SMYD3, a histone methylation transferase, was found to be expressed at higher levels in ascites-derived spheroids than in primary ovarian tumor cells from EOC patients." (PMID 34621667, 2021). "IHC demonstrated that SMYD3 tended to be cytoplasmic in ovarian tumor samples, and that SMYD3 expression gradually increased from normal ovaries, fallopian tubes, primary cancer lesions, to metastatic lesions." (PMID 33637115, 2021).
periodontitis (2 papers, 2021 to 2025). An acute or chronic inflammatory process that affects the tissues that surround and support the teeth. "In OSCC tissues specimens from patients with periodontitis, higher expression of lipopolysaccharide (LPS)-induced TSCC-associated transcript (LTSCCAT) and SMYD3 was associated with progression, lymph node metastasis, and decreased overall survival." (PMID 40924302, 2025). "Reverse transcription-polymerase chain reaction (RT-PCR) showed that the SMYD3 expression in tissues from TSCC patients with periodontitis was higher than that in TSCC patients without periodontitis." (PMID 33542221, 2021). "Our results demonstrated for the first time that LTSCCAT promotes TSCC metastasis by targeting the miR-103a-2-5p/SMYD3/TWIST1 axis, which may be the theoretical and therapeutic basis for periodontitis to promote the progression of TSCC." (PMID 33542221, 2021).
renal carcinoma (2 papers, 2022 to 2025). A carcinoma arising from the epithelium of the renal parenchyma or the renal pelvis. "Overall, we delineated the role of the cancer cell‐intrinsic SMYD3‐SREBP1‐CD47 axis in promoting renal cancer cell escape from immune attack." (PMID 40548645, 2025). "CD47, a bridge between innate and adaptive immunity, acts as the downstream effector molecule of the SMYD3 signal to promote the infiltration of T helper 2 (Th2) cells, protecting renal cancer cells from immune attack." (PMID 40548645, 2025).
schizophrenia (2 papers, 2023). A major psychotic disorder characterized by abnormalities in the perception or expression of reality. "We have also evaluated the performance of the NRVAT model using schizophrenia and bipolar disorder data and we have found an association signal with the SZ binary trait for one gene SMYD3, and with the BP binary trait for two genes, C1ORF77 and CGI-96." (PMID 37832140, 2023). "Seven switch genes, NPAS3, ARHGAP15, LGALS3BP, DPP10, SMYD3, CPXCR1, and HLA-DRB5, were associated with known risk factors for schizophrenia." (PMID 36982982, 2023). "Likewise, NPAS3, ARHGAP15, LGALS3BP, DPP10, SMYD3, CPXCR1, and HLA-DRB5 were associated with known risk factors for schizophrenia." (PMID 36982982, 2023).
small cell lung carcinoma (2 papers, 2022 to 2023). Small cell lung cancer (SCLC) is a highly aggressive malignant neoplasm, accounting for 10-15% of lung cancer cases, characterized byrapid growth, and early metastasis. "The latest research suggested that SMYD3-mediated methylation of RNF113A impedes small cell lung cancer sensitivity to DNA alkylation damage." (PMID 37237385, 2023). "RNF113A methylation by SMYD3 improves alkylation damage response and impairs small cell lung cancer sensitivity to alkylation-based chemotherapy." (PMID 35819319, 2022).
adenoma (1 paper, 2013). A neoplasm arising from the epithelium. "Quantitative analysis of microarray data confirmed that these methyltransferases, which included Setd3, Setd5, Suv39h2, Smyd3, Prmt3, Prmt6, Nsd1, and Nsd2 were up-regulated in metastases compared to adenomas, carcinomas, or disseminated cells." (PMID 23520493, 2013).
atherosclerosis (1 paper, 2020). A disease characterized by the build-up of fatty material and calcium deposition in the arterial wall resulting in partial or complete occlusion of the arterial lumen. "Since senescence has been detected in cells at sites of arteries prone to atherosclerosis or chronic arterial hypertension in human and experimental animal (Wang, Kim, Monticone, & Lakatta, 2015), we are curious whether Smyd3 and p21 also showed upregulated expression in related models." (PMID 32779886, 2020).
bladder tumors (1 paper, 2020). "In addition, we examined the SMYD3 expression in 70 BC tissues obtained in transurethral resection of bladder tumors (TURBT)." (PMID 32007952, 2020).
Chagas disease (1 paper, 2022). A parasitic infection caused by Trypanosoma cruzi. "All those genes are involved in biological process associated to Chagas disease: nervous system (LHX6, POU6F2, MDGA1, DISC1, PCSK9), immune system (ZMIZ, HLA-DRB1), Wnt pathway (DISC1), ion transport (KCNK15, PCSK9), striated muscles (SMYD3) or ATP metabolic process (ATP5S)." (PMID 36248819, 2022).
Chiari malformation (1 paper, 2021). A rare genetic brain malformation characterized by displacement of the brain stem and cerebellum through the foramen magnum. "Altogether, in both the cases, the rarity of the SMYD3 variants and their segregation with C1M suggest their role in Chiari malformation." (PMID 33337535, 2021).
ciliopathies (1 paper, 2024). "This study demonstrates that the histone methyltransferase, SMYD3, plays distinct roles in the spatiotemporal organization of the primary cilium, thus suggesting that SMYD3 may play a role in the pathophysiology of ciliopathy-related diseases." (PMID 38892227, 2024). "This study identified SMYD3 as a novel regulator of ciliogenesis that may contribute to the pathogenesis of ciliopathies and advanced our understanding of epigenetic mechanisms in cilia biogenesis." (PMID 38892227, 2024). "This study provides insights into the role of SMYD3 in cilia biology and suggests that SMYD3-mediated cilia formation/function may be relevant for cilia-dependent signaling in ciliopathies." (PMID 38892227, 2024).
cognitive decline (1 paper, 2023). "Future studies are needed to examine temporal patterns of epigenetic changes in AD, the mechanisms underlying epigenetic aberrations in AD, and whether inhibiting Smyd3 to restore NMDARs can ameliorate tau hyperphosphorylation and slow down cognitive decline." (PMID 36609445, 2023).
Cognitive impairment (1 paper, 2023). Abnormal cognition is characterized by deficits in thinking, reasoning, or remembering. "Taken together, these behavioral data indicate that cognitive impairment in Tau mice can be effectively mitigated by inhibiting Smyd3." (PMID 36609445, 2023). "Viral-based knockdown of Fbxo2 in PFC restores NMDAR-EPSC, leading to the amelioration of cognitive deficits, further confirming the important role of Smyd3-Fbxo2-NR1 pathway in AD pathophysiology." (PMID 36609445, 2023). "Next, we performed behavioral assays to examine the impact of Smyd3 inhibition on cognitive deficits in Tau mice." (PMID 36609445, 2023). "If so, future studies are needed to test whether inhibiting Smyd3 can ameliorate synaptic and cognitive deficits in 5xFAD mice." (PMID 36609445, 2023). "Indeed, a short (3-day) treatment with the Smyd3 inhibitor BCI-121 ameliorates cognitive deficits in P301S Tau mice." (PMID 36609445, 2023).
colon adenocarcinoma (1 paper, 2021). "At 100 uM, BCI-121 was also able to reduce the expression of SMYD3-target genes in the colon adenocarcinoma cell lines, indicating the drug’s ability to prevent SMYD3 recruitment at promoter sites." (PMID 33637115, 2021).
cystic kidneys (1 paper, 2024). "We further showed that SMYD3 is located at the centrosome and engages in the modulation of genome instability (centrosome amplification and mitosis/cytokinesis defects) and ciliogenesis in cystic kidneys." (PMID 38540216, 2024).
developmental delay (1 paper, 2023). "As demonstrated in the DECIPHER database, two cases with 1q44 microdeletion (DECIPHER ID: 338648 and 426113) only containing SMYD3 gene exhibited global developmental delay, intellectual disability, seizures, and stereotypy." (PMID 36624491, 2023).
gastric tumors (1 paper, 2024). "Our data showed that SMYD3 expression was significantly higher in chemoresistant than in nonresistant rectal and gastric tumors." (PMID 38812026, 2024).
head and neck squamous cell carcinoma (1 paper, 2023). A squamous cell carcinoma that arises from any of the following anatomic sites: lip and oral cavity, nasal cavity, paranasal sinuses, pharynx, larynx, and salivary glands. "Moreover, recent studies identified SMYD3 as a mediator of immune escape in human papilloma virus (HPV)-negative head and neck squamous cell carcinoma (HNSCC)." (PMID 37998381, 2023).
Hyperglycemia (1 paper, 2020). An increased concentration of glucose in the blood. "Hyperglycemia inhibited downregulation of S100 genes by both SET7 and SMYD3 inhibition." (PMID 32582175, 2020).
intrahepatic cholangiocarcinoma (1 paper, 2020). A carcinoma that arises from the intrahepatic bile duct epithelium in any site of the intrahepatic biliary tree. "miR124 directly associates with SMYD3 3’UTR and miR124 downregulation in Hepatitis C virus (HCV)-related intrahepatic cholangiocarcinoma (HCV-ICC) is linked to SMYD3 upregulation." (PMID 31935919, 2020).
lentivirus infection (1 paper, 2022). Virus diseases caused by the Lentivirus genus. "However, reconstitution of Smyd3 by lentivirus infection in Smyd3-/- MEF cells recovered the induction of expression of Pgk1 and Vegf compared to the empty virus control (pHAGE)." (PMID 36273580, 2022).